YARS2 (tyrosyl-tRNA synthetase 2)
Description:
Catalyzes the attachment of tyrosine to tRNA(Tyr) in a two-step reaction: tyrosine is first activated by ATP to form Tyr-AMP and then transferred to the acceptor end of tRNA(Tyr).
Synonyms: TyrRS; CGI-04; FLJ13995; mt-TyrRS; MLASA2
Tractability: Small molecule: a structure with a bound ligand is known; it has a high-quality binding pocket. PROTAC: ubiquitination databases record sites on it; its protein half-life has been measured.
Gene: Protein-coding gene on chromosome 12 (32,727,490 to 32,755,906, reverse strand). Ensembl gene ENSG00000139131.
Subcellular location: Mitochondrion matrix
Subcellular location (Human Protein Atlas): Mitochondria; Nuclear bodies
Pathways (Reactome):
Metabolism of proteins: Mitochondrial tRNA aminoacylation
Gene Ontology:
Molecular function: L-tyrosine binding; protein binding; protein homodimerization activity; RNA binding; tRNA binding; tyrosine-tRNA ligase activity; ATP binding; aminoacyl-tRNA ligase activity; nucleotide binding
Biological process: mitochondrial tyrosyl-tRNA aminoacylation; tRNA aminoacylation; translation; tRNA aminoacylation for protein translation; tyrosyl-tRNA aminoacylation
Cellular component: mitochondrial matrix; mitochondrion
Genetic constraint (gnomAD): Loss-of-function variants: 38 observed, 48.11 expected, observed/expected ratio (o/e) 0.79, 90% interval 0.61 to 1.03. The upper end of that interval is the gene's LOEUF score, 1.03, which puts it in group 4 of 6, group 1 being the genes least tolerant of losing a copy. Missense variants: 602 observed, 641.69 expected, observed/expected ratio (o/e) 0.94, 90% interval 0.88 to 1. Synonymous variants: 287 observed, 264.15 expected, observed/expected ratio (o/e) 1.09, 90% interval 0.99 to 1.2.
Gene-disease validity (ClinGen):
ClinGen rates the evidence that YARS2 causes each of these diseases.
mitochondrial disease (autosomal recessive): Definitive.
Homologues: Orthologues: chimpanzee YARS2 (99% identical), macaque YARS2 (98% identical), pig YARS2 (90% identical), dog YARS2 (87% identical), rabbit YARS2 (87% identical), guinea pig YARS2 (87% identical), mouse Yars2 (84% identical), rat Yars2 (79% identical), tropical clawed frog yars2 (61% identical), zebrafish yars2 (60% identical), Drosophila melanogaster TyrRS-m (44% identical), Caenorhabditis elegans yars-2 (32% identical).
Diseases named in the same sentence as YARS2 in open-access papers:
YARS2 is named in the same sentence as 39 diseases in open-access papers, as found by Europe PMC text mining. Sharing a sentence is not in itself a finding about the gene and the disease. The quoted sentences say what the papers report.
lactic acidosis (9 papers, 2013 to 2025). Metabolic acidosis characterized by the accumulation of lactate in the body. "Variants in YARS2 have been recently associated with myopathy, lactic acidosis, and sideroblastic anemia 2 (MLASA2)." (PMID 41226098, 2025). "Pathogenic variants in the mitochondrial tyrosyl-tRNA synthetase gene (YARS2) were associated with myopathy, lactic acidosis, and sideroblastic anemia (MLASA)." (PMID 34441767, 2021). "In human patients, YARS2 variants cause a phenotype termed myopathy, lactic acidosis, and sideroblastic anemia 2 (MLASA2; OMIM#613561)." (PMID 32183361, 2020). "Human patients with loss-of-function variants in YARS2 suffer from myopathy, lactic acidosis, and sideroblastic anemia 2, a disease with clinical similarities to the phenotype of the studied dogs." (PMID 32183361, 2020). "At least twelve human diseases have been associated with mutations in nuclear-encoded mt-aaRSs, and mutations in the human mt-TyrRS gene YARS2 cause myopathy, lactic acidosis, and sideroblastic anemia." (PMID 23382693, 2013). "Mutations in the mitochondrial tyrosyl-tRNA synthetase (YARS2) gene have previously been identified as a cause of the tissue specific mitochondrial respiratory chain (RC) disorder, Myopathy, Lactic Acidosis, Sideroblastic Anaemia (MLASA)." (PMID 24344687, 2013). "Notably, biallelic YARS2 variants cause myopathy, lactic acidosis, and sideroblastic anemia (MLASA2), a well-characterized syndrome." (PMID 41404429, 2025). "YARS2 deficiency causes myopathy, lactic acidosis, and sideroblastic anemia (MLASA2)." (PMID 41404429, 2025). "A tree-and-leaf plot showed that the JARID2 genome-wide DNA methylation change is most closely related to the DNA methylation changes of Coffin–Siris syndrome-9 (CSS9; SOX11), myopathy, lactic acidosis, and sideroblastic anemia 2 (MLASA2; YARS2) and Lysine-demethylase 2B (KDM2B)." (PMID 37762546, 2023). "YARS2 and PUS1 mutation screening was performed on a cohort of ten French or Italian patients with demonstrated RC enzyme deficiency who also presented with anaemia and at least one of the other MLASA features, ie. lactic acidosis or myopathy." (PMID 24344687, 2013). "Common features in patients with pathogenic YARS2 mutations are enzyme deficiencies of complexes I, III and IV in muscle, sideroblastic anaemia (although onset and duration may vary between patients), lactic acidosis, and skeletal myopathy and/or cardiomyopathy." (PMID 24344687, 2013).
sideroblastic anemia (7 papers, 2013 to 2025). "In any case, future studies should identify the optimal therapy and cofactors for achieving an optimal response in congenital sideroblastic anemia caused by YARS2 mutations and determine whether the anemia is self-limited." (PMID 41465467, 2025). "Therefore, the present findings open the doors to evaluate YARS2 deficits in heterogeneous forms of disease in association to isolated sideroblastic anemia, atypical presentations of MLASA and even in other mitochondrial myopathies of unknown origin." (PMID 34441767, 2021). "To date, six genes have been discovered that may cause sideroblastic anemia: PUS1, YARS2, LARS2, TNRNT1, NDUFB11 and MT-ATP6." (PMID 34441767, 2021).
anemia (3 papers, 2013 to 2025). A reduction in the number of red blood cells, the amount of hemoglobin, and/or the volume of packed red blood cells. "Here we refine the clinical spectrum associated with YARS2 mutations through mutation screening of a cohort of mitochondrial RC disorder patients with anaemia." (PMID 24344687, 2013). "In this study, a cohort of patients with a mitochondrial RC disorder for who anaemia was a feature, were screened for mutations in YARS2." (PMID 24344687, 2013). "However, it is possible that YARS2 mutations may be identified in RC disorder patients with alternate phenotypes in future, as our cohort was selected based on presence of anaemia." (PMID 24344687, 2013).
Mitochondrial myopathy (3 papers, 2013 to 2021). "Mutations in YARS2 can lead to mitochondrial respiratory chain complex deficiencies and are related to mitochondrial myopathy." (PMID 33888058, 2021). "We also examined the basis for the tissue-specific manifestation of YARS2 mitochondrial myopathy." (PMID 24344687, 2013).
Pearson syndrome (3 papers, 2016 to 2022). Pearson syndrome is characterized by refractory sideroblastic anemia, vacuolization of bone marrow precursors and exocrine pancreatic dysfunction. "Therefore, the siblings described in this paper, harboring YARS2 variants, present a phenotype that was clinically diagnosed as Pearson’s syndrome with an unusual benign course that, with the advent of NGS, has been finally diagnosed as MLASA2." (PMID 34441767, 2021). "Molecular study of YARS2 gene should be considered in patients presenting Pearson’s syndrome characteristics and MLASA related phenotypes." (PMID 34441767, 2021).
Skeletal myopathy (2 papers, 2013 to 2024). "Of interest are myocytes, as skeletal myopathy is the most notable feature of clinical cases of YARS2 variants, and additionally peripheral neurons, which are affected in most clinical cases of ARS2 variants." (PMID 39675712, 2024).
colon cancer (1 paper, 2022). "Knockdown of YARS2 in human colon cancer cell-line SW620 leads to significant inhibition of cell proliferation and migration." (PMID 36154909, 2022). "Then, we adopted human colon cancer cell-line SW620 as a cultured model and knocked down YARS2 expression." (PMID 36154909, 2022).
colorectal cancer (1 paper, 2022). A primary or metastatic malignant neoplasm that affects the colon or rectum. "In the present study, we evaluated transcript levels of mitochondrial tyrosyl-tRNA synthetase YARS2 in both colorectal cancer tissues and normal colorectal tissues using qRT-PCR." (PMID 36154909, 2022). "The results revealed that the mRNA expression level of YARS2 in colorectal cancer tissues was significantly higher than those in normal intestinal tissues." (PMID 36154909, 2022). "In conclusion, our study revealed that targeting YARS2 could inhibit colorectal cancer progression." (PMID 36154909, 2022).
melanoma (1 paper, 2014). A malignant, usually aggressive tumor composed of atypical, neoplastic melanocytes. "For example PPIP5K1->CATSPER2 and YARS2->NAP1L1 have been predicted in melanoma samples." (PMID 25133550, 2014).
nemaline myopathy (1 paper, 2023). Nemaline myopathy (NM) encompasses a large spectrum of myopathies characterized by hypotonia, weakness and depressed or absent deep tendon reflexes, with pathologic evidence of nemaline bodies (rods) on muscle biopsy. "Additionally, we identified a 3′ UTR variant in KLHL40 in a patient with nemaline myopathy 8 and a missense variant in YARS2 in a patient with a mitochondrial disorder known as MLASA2, both of which Introme helped prioritise as candidate splice-altering variants." (PMID 37198692, 2023).
pancreatic insufficiency (1 paper, 2021). "The newly identified missense variant c.1391T>C, p.(lle464Thr) and the premature stop codon c.314delG (p.(Gly105Alafs*4)) variant in YARS2 gene are responsible for a distinct phenotype of mitochondrial disease associating MLASA and pancreatic insufficiency." (PMID 34441767, 2021).
myopathy (12 papers, 2013 to 2025). A disease of the muscle in which the muscle fibers do not function properly. "Mutations within another mitochondrial ARS, tyrosyl-tRNA synthetase (YARS2) have been identified in a patient presenting with lactic acidosis, sideroblastic anemia and myopathy associated with a severe deficiency in respiratory chain enzyme function." (PMID 24669931, 2014). "MOWS clustered in a branch close to myopathy, lactic acidosis and sideroblastic anemia 2 (MLASA2) caused by pathogenic variants in YARS2." (PMID 38351292, 2024). "While exercise intolerance and myopathy are somewhat consistent with an effect on skeletal muscle shared with MLASA, CPEO and FSGS affect two distinct tissue types—the ocular system and kidneys, respectively—that are not affected by the variants in YARS2." (PMID 36553587, 2022).
tumor (3 papers, 2020 to 2024). "The data showed that the mRNA expression of YARS2 was overexpressed in CRC tissues compared to non-tumor control tissues (P < .01)." (PMID 36154909, 2022). "The tumor size was significantly smaller in the YARS2 knockdown group by day 15 after cell implantation (P < .01), and the differences were enlarged along with the progress of the experiment." (PMID 36154909, 2022). "Remarkably, specific aaRS genes do show a DNA profile reminiscent of an oncogene (e.g., GARS1, AIMP2, and YARS2) or tumor suppressor (e.g., NARS1, QARS1, LARS2, and RARS2)." (PMID 33266490, 2020). "In addition, YARS2, a member of mitochondrial tyrosine-tRNA synthetase, exhibits aberrant expression in numerous tumors, correlating with enhanced tumor proliferation and migration." (PMID 39238386, 2024). "Moreover, YARS2 knockdown SW620 cells showed a reduced level of ATP which may be responsible for the inhibited cell proliferation and tumor growth." (PMID 36154909, 2022).
cancer (2 papers, 2020 to 2022). A tumor composed of atypical neoplastic, often pleomorphic cells that invade other tissues. "TARS1, VARS1, CARS2, DARS2, and YARS2 are associated with unfavorable outcomes in two cancer types." (PMID 33266490, 2020). "Further analysis showed that all of these dysregulated proteins had cancer-related associations, such as PDIA5, DEF6, MZB1, TXNDC5, YARS2, MGST1, and PIH1D1." (PMID 35958927, 2022). "Specific aaRSs that are differentially upregulated across many cancer types include TARS1 (n = 23), DARS2 (n = 22), GARS1 (n = 21), YARS2 (n = 21), EPRS1 (n = 20), AIMP2 (n = 19), and FARSA (n = 18)." (PMID 33266490, 2020).
cardiovascular disorder (1 paper, 2024). A disease involving the cardiovascular system. "Tyrosyl‐tRNA synthetase, mitochondrial (YARS2) is inhibited by tyrosine, its levels increase during aging, neurocognitive, metabolic, and cardiovascular disorders." (PMID 38346717, 2024).
genetic diseases (1 paper, 2024). "This problem is not unique to YARS2 but is common to all human genetic diseases, representing a major challenge in modern genetic medicine." (PMID 39675712, 2024).
metabolic disorder (1 paper, 2024). "In the tree-and-leaf representation MOWS shares a branch with MLASA2, a metabolic disorder caused by defects in a mitochondrial tRNA synthase encoded by YARS2." (PMID 38351292, 2024).
renal disease (1 paper, 2025). "Only two mt-ARS deficiencies are primarily associated with extra-CNS manifestations: SARS2, linked to renal disease, and YARS2, which causes the MLASA2 phenotype." (PMID 41404429, 2025).
YARS2 also shares sentences with these, for which no sentence is quoted: sideroblastic anemia 2 (4 papers); cardiomyopathy (2); Alkalosis (1); Coffin–Siris syndrome-9 (1); deafness (1); deficiencies (1); delirium (1); epilepsy (1); Epiphyseal dysplasia (1); hypertrophic cardiomyopathy (1); hyperuricemia (1); Leber hereditary optic neuropathy (1); liver failure (1); mitochondrial disease (1); myocardial hypertrophy (1); pancytopaenia (1); renal failure (1); scoliosis (1); skeletal dysplasia (1); viral infection (1); Visual impairment (1).